OCRL (OCRL inositol polyphosphate-5-phosphatase)
Diseases named in the same sentence as OCRL in open-access papers (continued):
Sharing a sentence is not in itself a finding about the gene and the disease.
Lowe syndrome (continued). "Lowe syndrome is caused by mutations in the OCRL gene, which is located on chromosome Xq26 (#300535)." (PMID 31676009, 2019). "According to international literature, pathogenic mutations to OCRL gene cause Lowe syndrome (#309000) and Dent disease (#300555) in an X-linked recessive inheritance pattern." (PMID 31676009, 2019). "This approach allowed us to categorize three exonic OCRL mutations associated with Lowe syndrome, c.741G>T; p.(Trp247Cys), c.2581G>A; p.(Ala861Thr) and c.2581G>C; p.(Ala861Pro) as splicing mutations." (PMID 29300302, 2018). "Single-base substitutions in the OCRL gene, many of which are predicted to lead to missense mutations, are often found in patients with Lowe syndrome or Dent-2 disease." (PMID 29300302, 2018). "Lowe syndrome and Dent-2 disease are caused by mutations in the OCRL gene located on chromosome Xq26.1." (PMID 29300302, 2018). "Lowe syndrome (LS) is a rare genetic disorder caused by loss of function mutations in the X-linked gene, OCRL, which codes for inositol polyphosphate 5-phosphatase." (PMID 30147856, 2018). "We have established an iPS cell model for Lowe syndrome, a rare X-linked disorders caused by loss of function mutations in OCRL, which codes for inositol polyphosphate 5-phosphatase, a regulator of endosome recycling and actin dynamics." (PMID 30147856, 2018). "We made retinal pigmented epithelial (RPE-1) cells deficient in OCRL and similar to mutations that occur in Lowe syndrome by targeting exon 9 using CRISPR-Cas9D10A nickase–based genome editing." (PMID 28923975, 2017). "Deficiencies in OCRL cause Lowe syndrome, a multisystem genetic condition characterized by congenital cataracts, intellectual disability, and kidney absorption problems (Bökenkamp and Ludwig, 2016)." (PMID 28923975, 2017). "Lowe syndrome is an X-linked disorder caused by mutations in the phosphoinositide-5-phosphatase OCRL (Oculocerebrorenal Syndrome of Lowe)." (PMID 29028801, 2017). "Lowe syndrome is a developmental disorder characterized by severe kidney, eye, and neurological symptoms, and is caused by mutations in the gene OCRL." (PMID 29028801, 2017). "ASH domains are normally found in proteins that localize to cilia, such as Hydin and OCRL which are associated with microcephaly and Lowe oculocerebrorenal syndrome respectively." (PMID 29333229, 2016). "The causative oculocerebrorenal syndrome of Lowe gene (OCRL) encodes the inositol polyphosphate 5-phosphatase OCRL-1." (PMID 27011217, 2016). "OCRL variants have not only been found in classic Lowe syndrome, but also in patients with a predominantly renal phenotype classified as Dent disease type 2 (Dent-2)." (PMID 27011217, 2016). "Here, we review the phenotypic features of Lowe syndrome, the molecular genetics of OCRL variants, and the current understanding of the physiological functions of OCRL-1." (PMID 27011217, 2016). "CLCN5 encodes the electrogenic chloride/proton exchanger ClC-5 which is involved in the tubular reabsorption of albumin and LMW proteins, OCRL encodes the inositol polyphosphate 5-phosphatase, and was initially associated with Lowe syndrome." (PMID 26389017, 2015). "Mutations in the OCRL gene, encoding the inositol polyphosphate 5-phosphatase, initially associated with Lowe syndrome, account for 15 % of the patients now classified as having Dent disease 2 (DD2) (OMIM 300555)." (PMID 26389017, 2015). "Mutations in one such gene, OCRL, give rise to Oculo-Cerebro-Renal syndrome of Lowe (Lowe syndrome) and type 2 Dent's disease, two X-linked diseases." (PMID 25107275, 2014). "The complexity of OCRL function is highlighted by the multiple defects observed in patients with Lowe's syndrome, which have mutations in OCRL." (PMID 24992562, 2014). "Here we show that OCRL loss in Lowe syndrome patient fibroblasts impacts clathrin-mediated endocytosis and results in an endocytic defect." (PMID 25107275, 2014).
Lowe syndrome (continued). "OCRL mutations have been found in Lowe syndrome, which usually presents with bilateral congenital cataracts and glaucoma; however, the pathogenesis of these ocular phenotypes is not known." (PMID 23805271, 2013). "Mutations in OCRL, an inositol polyphosphate 5-phosphatase, result in Oculocerebrorenal syndrome of Lowe, an X-linked recessive disorder that presents with congenital cataracts, glaucoma, renal dysfunction and mental retardation." (PMID 23805271, 2013). "Dent disease-2 and Lowe syndrome are associated with OCRL gene variants." (PMID 40485688, 2025). "Additionally, two diseases, Lowe syndrome and Dent disease type 2, result from mutations in the OCRL gene with some overlap in affected exons." (PMID 41278199, 2025). "Additionally, two diseases, both Lowe syndrome and Dent 2, result from mutations in the same OCRL gene, and some patients even have mutations at the same gene site but different clinical symptoms." (PMID 41278199, 2025). "However, genetic background is also a likely factor considering that in some cases the same mutation in OCRL can result in either Dent-2 disease or Lowe syndrome, and Lowe syndrome of varying severity can also result from the same mutation in OCRL." (PMID 40778266, 2025). "Mutation of OCRL can cause Lowe syndrome, which includes congenital cataract and glaucoma." (PMID 37378878, 2024). "Mutations in the oculocerebrorenal syndrome of Lowe (OCRL) gene are responsible for Lowe syndrome." (PMID 39553960, 2024). "To determine whether OCRL mutations influence neuronal development, we developed an in vitro system of functional induced neuron (iN) cells differentiated from Lowe syndrome patient-derived iPSCs." (PMID 39553960, 2024). "OCRL is an inositol polyphosphate 5-phosphatase, which is mutated in Lowe syndrome." (PMID 38903773, 2024). "The OCRL gene, previously associated with Lowe’s oculocerebrorenal syndrome, encodes an inositol polyphosphate-5-phosphatase (OCRL1), located in the Golgi apparatus and in early endosomes, that may play a role in trafficking and cellular endocytosis." (PMID 38002082, 2023). "Lowe syndrome is caused by variants in the OCRL gene on chromosome Xq25-26." (PMID 35919034, 2022). "Both Lowe syndrome and Dent-2 disease are caused by variants in the OCRL gene." (PMID 35919034, 2022). "In addition to Dent disease, CLCN5 associated disease have a variable phenotype including focal segmental glomerulosclerosis (FSGS), and the OCRL path variants are also associated with Oculocerebrorenal syndrome." (PMID 33430795, 2021). "OCRL mutations also cause Lowe syndrome (LS) involving the eyes, brain and kidney." (PMID 34680992, 2021). "Similar to INPP5E, OCRL also regulates autophagosome-lysosome fusion; loss of catalytic activity of OCRL causes autophagosome accumulation and lysosomal dysfunction in cells isolated from patients with Lowe syndrome." (PMID 34414314, 2021). "Lowe syndrome and Dent II disease are X-linked monogenetic diseases characterised by a renal reabsorption defect in the proximal tubules and caused by mutations in the OCRL gene, which codes for an inositol-5-phosphatase." (PMID 34069732, 2021). "Lowe syndrome is an X-linked monogenetic human disease mainly affecting the eye, brain, and kidney and, thus, is also known as oculocerebrorenal syndrome, which gave rise to the name OCRL for the gene mutated in Lowe syndrome." (PMID 34069732, 2021). "OCRL mutations, which may result in a spectrum of phenotypes ranging from Dent disease 2 to the more severe Lowe oculocerebrorenal syndrome, account for a further 15% of cases, whilst the underlying genetic mutation remains unascertained in 25% of cases." (PMID 31935940, 2020). "Although genetic conditions with a Fanconi syndrome, including Lowe oculocerebrorenal syndrome (OCRL mutations) and cystinosis (CTNS mutations) may also feature nephrocalcinosis, it remains more commonly associated with Dent disease 1 (CLCN5 mutations)." (PMID 31935940, 2020).
Lowe syndrome (continued). "We addressed this by investigating a key pair of endocytic adaptor proteins, PH domain-containing endocytic trafficking adaptor 1 and 2 (PHETA1/2; also known as FAM109A/B, Ses1/2, IPIP27A/B), which interact with the protein product of OCRL, the causative gene for Lowe syndrome." (PMID 32152089, 2020). "Dent disease type 2 is characterized by a broad phenotypic spectrum, depending on the OCRL mutations that are responsible, implying that this particular disease may be a mild variant/phenotype of Lowe syndrome." (PMID 31676009, 2019). "Mutations in the OCRL gene are associated with both Lowe syndrome and Dent-2 disease." (PMID 29300302, 2018). "There is a broad phenotypic spectrum of OCRL mutations and Dent disease 2 may be a mild variant of Lowe syndrome characterized by hydrophthalmia, cataract, mental retardation, HR, amino aciduria, proteinuria and phosphaturia." (PMID 29280738, 2017). "Thus, our work uncovers a new function for OCRL in animals, and opens an exciting new avenue of investigation into how loss of OCRL causes the symptoms of Lowe syndrome." (PMID 29028801, 2017). "Lowe Syndrome is a developmental disorder characterized by eye, kidney, and neurological pathologies, and is caused by mutations in the phosphatidylinositol-5-phosphatase OCRL." (PMID 29028801, 2017). "One example is Lowe syndrome, an X-linked disorder caused by OCRL mutations." (PMID 28190456, 2017). "Mutations in the inositol 5-phosphatase OCRL cause Lowe syndrome and Dent's disease." (PMID 25107275, 2014). "Lowe syndrome results from mutations in OCRL, a type II inositol polyphosphate 5-phosphatase." (PMID 23805271, 2013). "Recent studies of OCRL variant transcripts and splicing assays in a minigene system suggest that differences in Ocrl1 isoform expression leading to truncation or aberrant splicing help account for some of the genotype/phenotype variation between Dent 2 and Lowe syndrome." (PMID 41278199, 2025). "Lowe Syndrome (LS) is a rare X-linked genetic disease, also known as Oculo-Cerebro-Renal syndrome of Lowe (OCRL), caused by functional deficiencies of the lipid phosphatase OCRL1 (EC 3.1.3.36)." (PMID 37189363, 2023). "Among them, 34 in 48 cases of Lowe syndrome presented with truncating mutations, while 11 in 35 cases of Dent-2 disease presented with truncating mutation, demonstrating that truncating mutations of OCRL gene were more likely seen in patients with Lowe syndrome than Dent-2 disease." (PMID 35919034, 2022). "OCRL has been shown to control many steps of packaging and transport of materials within cells, though it remains unclear which of these disrupted transport steps cause each of the many symptoms in Lowe syndrome patients." (PMID 29028801, 2017). "The pathological manifestations of Lowe syndrome and Dent's disease are thought to arise from abnormal protein sorting and membrane recycling, as loss of OCRL would disrupt the appropriate coordination between membrane progression and changes in phosphoinositide composition." (PMID 25107275, 2014). "Together, these observations indicate excellent conservation of OCRL between humans and zebrafish, supporting its use as a model for Lowe syndrome and Dent-2 disease." (PMID 40778266, 2025). "Of note, both a Lowe syndrome and DD2 phenotype have been reported for five OCRL variants, arguing against a clear genotype–phenotype effect." (PMID 39794284, 2025). "In this review I will discuss the use of zebrafish as an animal model to better understand the roles of OCRL in vivo and the pathology of Lowe syndrome and Dent-2 disease." (PMID 40778266, 2025). "OCRL was originally described as the gene responsible for Lowe syndrome (OMIM: 309000), a condition characterized by congenital cataracts, Fanconi syndrome, muscle weakness, and psychomotor developmental delay." (PMID 40163114, 2025).
Lowe syndrome (continued). "The first zebrafish model to study Lowe syndrome and Dent-2 disease was generated using a genetrap approach, resulting in a zebrafish mutant containing a retroviral insertion close to the OCRL promoter." (PMID 40778266, 2025). "Using both the stable OCRL genetrap model and a translation blocking OCRL morpholino, it was shown that attenuation of OCRL expression manifests as several neurological features similar to those seen in Lowe syndrome patients." (PMID 40778266, 2025). "Mutations in OCRL1 that encodes for inositol-5-phosphatase, another Rab8 effector cause the X-linked oculocerebrorenal syndrome of Lowe (OCRL) or Lowe syndrome which manifests with abnormal primary cilia." (PMID 40395934, 2025). "The zebrafish model has proven informative for understanding the functional role of OCRL in vivo, as well as providing insights into the pathology of Lowe syndrome and Dent-2 disease." (PMID 40778266, 2025). "Cases associated with OCRL variants demonstrated that truncating variants in OCRL exons 1 to 7 results in Dent disease-2; whereas in 8 to 24, they result in Lowe syndrome, indicating that OCRL isoforms are responsible for differences in disease severity." (PMID 40485688, 2025). "The zebrafish model complements these other models, allowing a better understanding of OCRL function in vivo, the mechanisms of Lowe syndrome and Dent-2 disease, and the discovery of new drug treatments for these conditions." (PMID 40778266, 2025). "We found that induced neuronal (iN) cells derived from mutant-OCRL iPSCs are more responsive to differentiation to astrocytes than iPSCs derived from wild-type OCRL and that a Lowe syndrome mouse model that lacks OCRL shows a similar pattern." (PMID 39553960, 2024). "The hemizygous c.2581G>A/p.Ala861Thr of the OCRL was identified in a patient suspected of Lowe syndrome (Case gs6)." (PMID 38785568, 2024). "Similar to the OCRL gene previously reported, the mutation will not only cause Dent disease type 2 (DD2) but also cause Lowe syndrome (LS) involving the eyes, brain and kidney." (PMID 37217920, 2023). "It demonstrates that the Golgi/trans-Golgi network is not the only organelle affected by loss of OCRL function and raises the question of the role of OCRL-induced PM perturbation in the pathophysiology of Lowe syndrome." (PMID 37172724, 2023). "In the present study, 48 consecutive Chinese children with Lowe syndrome and 35 with Dent-2 disease from published or new data were collected and reanalyzed to further understand the phenotype-genotype correlation of the OCRL gene." (PMID 35919034, 2022). "Lowe Syndrome (LS) is a human pathological and lethal condition caused by mutations in the OCRL gene, encoding a phosphatidylinositol 5-phosphatase OCRL1, affecting the brain, eye, and kidney." (PMID 36340038, 2022). "Defects such as neurodevelopmental delay, cataract, and hypotonia are features of the oculocerebrorenal syndrome of Lowe, reflecting the broader expression of OCRL (kidney, eye, and brain) vis-à-vis ClC-5, which is mainly expressed in the kidney." (PMID 32860533, 2021). "We corrected the diagnosis of four cases of Alport syndrome (COL4A5, n = 1), Lowe syndrome (OCRL, n = 2) and Dent disease (CLCN5, n = 1)." (PMID 36939782, 2021). "It emerged that patients with Lowe syndrome lack OCRL expression in the Golgi and the lysosomes of all cell types analyzed." (PMID 32860533, 2021). "A step forward came with a study on proximal tubular cells from patients with Lowe syndrome, which identified an essential role for OCRL in early endosome function, and in vesicular trafficking defects due to a damaged F-actin filaments architecture." (PMID 32860533, 2021). "In order to develop an organ on chip model for Lowe syndrome, we first engineered a suitable cellular model for Lowe syndrome by deleting OCRL protein expression in the human proximal tubule cell line HK-2 using CRISPR/Cas9." (PMID 34069732, 2021).
Lowe syndrome (continued). "Using our in vitro model for Lowe syndrome/Dent II disease, we performed RNA-seq on tubules formed either from wild-type or OCRL KO cells under fluid flow." (PMID 34069732, 2021). "Mutations in the OCRL gene cause both DD2 and Lowe syndrome, and a genotype–phenotype correlation has been suggested." (PMID 32860533, 2021). "In line with previous reports, such OCRL KO cell lines recapitulate important phenotypes of Lowe syndrome including reduced megalin-dependent endocytosis and increased actin polymerisation around endosomes." (PMID 34069732, 2021). "Defects in synaptojanin-1 and INPP5E are associated with retinal defects, as is the phosphoinositide 5-phosphatase, OCRL (oculocerebrorenal syndrome of Lowe)." (PMID 32252387, 2020). "LMW proteinuria is a consistent feature observed in Lowe syndrome/Dent disease 2, revealing that OCRL affects receptor-mediated endocytosis." (PMID 32919786, 2020). "IPIP27 scaffolds the inositol phosphatase oculocerebrorenal syndrome of Lowe (OCRL) by coupling it to endocytic BAR domain proteins." (PMID 30799246, 2019). "The enzyme defective in Lowe’s syndrome, OCRL, is functionally similar to PIK3C2A as well, as it is also required for membrane trafficking and ciliogenesis." (PMID 31034465, 2019). "Case 9 had Lowe Oculocerebrorenal Syndrome (MIM#309000), which is known to be caused by mutations and deletions of the OCRL gene." (PMID 31149029, 2019). "Another host factor potentially involved in shaping the LCV PI pattern is the PI 5-phosphatase Oculocerebrorenal syndrome of Lowe (OCRL), which localizes to the TGN and endosomes and regulates retrograde trafficking between the two compartments." (PMID 30538188, 2018). "The Oculo-Cerebro-Renal syndrome of Lowe (OCRL), also known as Lowe syndrome (LS) is a genetic disease caused by mutations in the OCRL1 gene which encodes for an inositol 5-phosphatase (EC 3.1.3.36)." (PMID 29444177, 2018). "Dent disease 2 (MIM 300555, or Lowe syndrome or oculocerebrorenal syndrome, MIM 309000) is also an X-linked recessive disease caused by mutations in the OCRL gene (MIM 300535) which encodes inositol polyphosphate-5-phosphatase." (PMID 29280738, 2017). "In this review, we provide an update on clinical and molecular genetic findings in Lowe syndrome and the cellular and physiological functions of OCRL-1." (PMID 27011217, 2016). "Lowe syndrome is caused by variants in the OCRL gene on chromosome Xq25-26, which encodes OCRL-1, an inositol polyphosphate 5-phosphatase." (PMID 27011217, 2016). "Polarized membrane traffic during cilia formation is regulated via OCRL-1 and fibroblasts from Lowe syndrome patients or cell lines with knocked-down OCRL fail to form functional primary cilia." (PMID 27011217, 2016). "Prompted by these findings, we examined the contribution of OCRL to clathrin-mediated endocytosis in Lowe syndrome patient fibroblasts." (PMID 25107275, 2014). "Previously inositol phosphatases OCRL and INPP5E have been found to be implicated in Lowe syndrome and Joubert syndrome, respectively." (PMID 23805271, 2013). "Similar defects have been reported in OCRL-knockdown models and in Lowe syndrome." (PMID 40565289, 2025). "Lowe syndrome (oculo-cerebro-renal disease of Lowe) is a rare X-linked disorder with no specific therapy caused by pathologic variants of the OCRL gene." (PMID 41278199, 2025). "More recently, mutations in OCRL were also shown to cause Dent-2 disease, which shares the same renal pathology as Lowe syndrome but in which the extra-renal symptoms are either absent or milder than those seen in Lowe syndrome." (PMID 40778266, 2025). "OCRL-deficient zebrafish do not display an overt eye pathology, for example, cataracts, which is a hallmark of Lowe syndrome." (PMID 40778266, 2025). "However, in 20 patients (66.6%), the genetic testing revealed a different diagnosis, such as neurodevelopmental disorders (e.g., ZSWIM6-related disorder), deafness (GJB2-related), or Lowe syndrome (OCRL-related)." (PMID 38818036, 2024).